NTN1 (netrin 1)
Diseases named in the same sentence as NTN1 in open-access papers (continued):
Sharing a sentence is not in itself a finding about the gene and the disease.
myocardial infarction (10 papers, 2017 to 2022). Gross necrosis of the myocardium, as a result of interruption of the blood supply to the area, as in coronary thrombosis. "This study showed increased circulating netrin-1 levels in patients suffering from myocardial infarction or in mice exposed to in situ myocardial ischemia and reperfusion injury." (PMID 35910389, 2022). "Tissue-specific studies suggested a myeloid source of netrin, since mice with myeloid netrin-1 deletion (Ntrn1loxp/loxp LysMCre+) experienced larger myocardial infarct sizes, and showed attenuated netrin-1 blood levels." (PMID 35910389, 2022). "Netrin-1 regulates angiogenesis in response to ischemic insults and exerts a cardioprotective effect in myocardial infarctions via ERK1/2-dependent nitric oxide activation by endothelial nitric oxide synthase (eNOS)." (PMID 35621843, 2022). "Preconditioning with netrin-1 further reduces the myocardial infarct size and cardiomyocyte apoptosis through NO and ERK1/2 upregulation." (PMID 35008701, 2021). "In that, netrin-1 preserves mitochondrial function in cardiomyocytes and endothelial cells following myocardial infarction." (PMID 35008701, 2021). "Specifically, a progressive increase in Netrin-1 and UNC5b was evidenced going from controls to stable angina (SA) and acute myocardial infarction (AMI) patients." (PMID 33567662, 2021). "Zhang J, Cai H. Netrin-1 prevents ischemia/reperfusion-induced myocardial infarction via a DCC/ERK1/2/eNOS s1177/NO/DCC feed-forward mechanism." (PMID 32267322, 2020). "In conclusion, Aerobic exercise can improve myocardial fibrosis after myocardial infarction and promote the expression of netrin-1 and DCC receptors." (PMID 30789913, 2019). "Recently, in rodents, transplantation of either BM-MSC or AD-MSC with Netrin-1, has shown to improve the function of the sciatic nerve after injury and also to exert a protective role after myocardial infarction." (PMID 28241866, 2017). "In the model of ischemia/reperfusion-induced myocardial infarction, with Netrin-1 treatment, Netrin-1 receptors were detected, in which the mRNA and protein level of DCC were abundantly elevated, which is consistent with our research." (PMID 29321724, 2017). "Further, netrin-1 treatment has been shown to abolish autophagy which occurs in a coronary ligation model of myocardial infarction." (PMID 29059224, 2017). "Netrin-1 also ameliorates myocardial infarction in a diabetic animal model and abrogates I/R-induced cardiac mitochondrial dysfunction via NO-dependent attenuation of NADPH oxidase isoform 4 activity and recoupling of NOS." (PMID 29059224, 2017). "Consistent with a functional role of PMN-dependent netrin-1 in mediating DMOG-dependent cardioprotection, we found that the previously shown reduction of myocardial infarct sizes associated with DMOG treatment were completely abolished in Ntn1loxP/loxP LysM Cre+ mice." (PMID 36247475, 2022). "Recent studies from our laboratory demonstrated the mice with deletion of myeloid-expressed netrin-1 (Ntn1loxP/loxP LysM Cre+ mice) experience increased myocardial infarct sizes and show that elevated levels of netrin-1 during myocardial infarction predominantly stems from PMNs." (PMID 36247475, 2022). "Therefore, the present study was undertaken to investigate the changes in netrin- 1 expression after myocardial fibrosis, and evaluate the effect of aerobic exercise on netrin-1 after myocardial infarction." (PMID 30789913, 2019). "In the research of Zhang and Cai (2010), Netrin-1 protected the heart from myocardial infarction via the activation of the ERK signaling pathway, which was abolished by U0126, indicating that Netrin-1 plays a role in myocardial infarction via the ERK signaling pathway." (PMID 29321724, 2017). "However, measurements of cardiac or circulating levels of adenosine were not altered by treatment doses of recombinant netrin-1 that were associated with attenuated myocardial infarct sizes." (PMID 35910389, 2022).
myocardial infarction (continued). "Therefore, we hypothesized that serum and myocardial netrin-1 expression were decreased after myocardial infarction." (PMID 30789913, 2019). "This suggests that, in response to myocardial infarction and reperfusion, activation of HIF1A coordinates cardioprotective effects by activating the expressions of Netrin-1 and ADORA2B, which both reduce post-ischemic myocardial inflammation." (PMID 36247475, 2022). "Aerobic exercise increased levels of serum netrin-1, myocardial netrin-1, and the DCC receptor and reduced the expression of myocardial MMP2 and MMP9 proteins, to improve the degree of fibrosis following myocardial infarction in rats." (PMID 30789913, 2019). "Moreover, small netrin-1-derived peptides are highly effective in protecting the heart against myocardial IRI and have been proposed as drugs directly applicable to the treatment of myocardial infarctions." (PMID 35621843, 2022). "However, more importantly, aerobic exercise is likely to improve the degree of myocardial fibrosis after myocardial infarction by increasing the expression of serum and myocardial netrin-1, and this protective mechanism may involve binding of the DCC receptor with netrin-1." (PMID 30789913, 2019).
colon carcinoma (9 papers, 2020 to 2025). "Collectively, these findings point to increased NTN-1 during OB and CC fuelling cancer progression and exerting a strong migratory effect on colon cancer cells." (PMID 36831381, 2023). "Expression of Netrin-1 and its receptors has also been found play a role in tumorigenesis in several human cancers, such as breast and colon cancer." (PMID 36361539, 2022). "NTN1 is being secreted by the stroma and vessels of the NB primary tumors, corroborating prior literature pointing to an expression in lung and colon tumor stromal cells." (PMID 33724150, 2021). "Furthermore, netrin-1 selectively secreted by colon cancer cells activates the cAMP/PKA cascade in MDSCs, amplifying their immunosuppressive activity." (PMID 40969768, 2025). "However, NTN1 may play an important role in the early stages of adenoma progression into colon cancer." (PMID 37674118, 2023). "In the same vein, the Netrin-1/DCC guidance gene set, otherwise known as commissural axon pathfinding, contributes significantly to synapse formation and plasticity via two main components, Netrin-1 (ligand) and its receptor DCC (deleted in colon cancer)." (PMID 39000495, 2024).
inflammatory bowel disease (9 papers, 2012 to 2025). A spectrum of small and large bowel inflammatory diseases of unknown etiology. "Ntn-1, which is upregulated in the intestinal epithelium of patients with inflammatory bowel diseases (IBD), could be associated with intestinal epithelial damage by modulating leukocyte migration without directly affecting the epithelial barrier." (PMID 40004236, 2025). "Together, these studies implicate the netrin-1-Adora2b link in attenuating intestinal inflammation, as shown during inflammatory bowel disease." (PMID 35910389, 2022). "This indicates that the purinergic signaling pathway contributes to the favorable effects of netrin-1 in inflammatory bowel disease." (PMID 35008701, 2021). "Recent studies in various inflammation-based diseases, such as kidney ischemia reperfusion injury, hypoxia-induced inflammation, acute lung injury, peritonitis, and inflammatory bowel disease, showed that netrin-1 holds anti-inflammatory potential and can reduce local inflammatory tissue injury." (PMID 23029434, 2012). "In acute experimental colitis, a model for inflammatory bowel disease (IBD), netrin-1 is induced in the mucosal lining of the whole colon." (PMID 35008701, 2021). "Furthermore, netrin-1 has been shown to modulate inflammatory responses and reduce local tissue injury in several animal models, including kidney ischemia reperfusion injury, hypoxia-induced inflammation, acute lung injury, peritonitis, and inflammatory bowel disease." (PMID 23029434, 2012).
ovarian cancer (9 papers, 2011 to 2024). A primary or metastatic malignant neoplasm involving the ovary. "NTN1 (netrin-1) has been proved progressed in ovarian cancer and have the potential for the development of new diagnosis and treatment strategies for ovarian cancer." (PMID 37337170, 2023). "The expression of NTN1 was strongly upregulated in malignant ovarian tumors when compared with benign tumors." (PMID 35053566, 2022). "We were then able to analyse netrin-1 and receptors level in ovarian cancer specimens from patients before and after being treated with carboplatin/taxol." (PMID 24293316, 2013). "NTN1 was found overexpressed in 76% of ovarian cancer specimens (13/17) as compared to normal (0/10, p<0.004) and benign (1/8, p<0.008) samples." (PMID 21789787, 2011). "The fact that increased NTN1 is specifically observed in cancerous tissues indicates that NTN1 may represent a novel candidate biomarker for ovarian cancer." (PMID 21789787, 2011). "Here, we demonstrated that NTN1 may be involved in ovarian cancer as the expression of NTN1 mRNA is strongly upregulated in ovarian malignant tumors but not in benign tumors." (PMID 21789787, 2011). "Thus, NTN1 might be a crucial regulator of ovarian cancer progression and a promising biomarker." (PMID 38546656, 2024). "Previous research has discovered that NTN1 is overexpressed in the vast majority of malignant ovarian tumours but not in benign tumours." (PMID 38546656, 2024). "Moreover, four neural genes (NTN1, UNC5B, EFNB2, and EFNA5) were nominated as promising biomarkers and therapeutic targets in ovarian cancer patients." (PMID 39456618, 2024). "Our purpose was to investigate whether NTN1 and its receptor DCC may be involved in ovarian cancer." (PMID 21789787, 2011).
pancreatic cancer (9 papers, 2013 to 2025). "Here, we show that epithelial NTN1 secretion, initiated by the KrasG12D mutation, not only enhances tumor cell growth directly but also promotes nerve axonogenesis toward pancreatic tumors, thereby accelerating tumor development and metastasis." (PMID 40777309, 2025). "A phase I clinical trial is ongoing to test the NTN1-blocking antibody NP137 in combination with FOLFIRINOX in patients with locally advanced pancreatic cancer (ClinicalTrials.gov identifier: NCT05546853)." (PMID 40777309, 2025). "Treatment of pancreatic tumor organoids with recombinant NTN1 enhanced cell growth, epithelial-mesenchymal transition (EMT), and cancer stemness with the upregulation of ZEB1 and SOX9 through NEO1-mediated activation of focal adhesion kinase (FAK)." (PMID 40777309, 2025). "Collectively, these data suggest that NTN1 secreted from Kras-mutant pancreatic tumor cells increases the axonogenesis of sympathetic nerves partly through NEO1." (PMID 40777309, 2025). "qRT-PCR from pancreatic tissues demonstrated that Ntn1 was upregulated in pancreatic tumors from KC and KPC mice compared with the normal pancreas from wild-type (WT) mice." (PMID 40777309, 2025). "Increased adrenergic inputs, in turn, upregulate NTN1 expression through the β-adrenergic receptor to drive a feedforward loop that promotes pancreatic tumor development." (PMID 40777309, 2025). "Netrin-1, transported via EVs from pancreatic cancer cells, initiates the activation of HSCs, culminating in liver metastasis." (PMID 38954230, 2024). "NTN1 inhibits the growth of early pancreatic cancer cells by inhibiting the MEK/ERK pathway and ITGB424." (PMID 32251318, 2020). "In contrast, study in pancreatic cancer have reported that netrin-1 inhibited tumor growth by interfering with integrin β4 expression through UNC5B/FAK signaling." (PMID 28710382, 2017). "We first characterized the netrin-1 expression pattern during PDAC progression using a human pancreatic cancer tissue array containing all stages of ductal adenocarcinoma and normal pancreatic tissue." (PMID 27034160, 2016). "Given the upregulation of NTN1 in pancreatic tumor cells by adrenergic stimulation, we examined whether there is crosstalk between NTN1-expressing PDAC cells and sympathetic nerves." (PMID 40777309, 2025). "Next, we examined the possible direct effects of NTN1 on pancreatic tumor cells." (PMID 40777309, 2025). "Ntn1 knockout inhibits innervation and pancreatic tumor development in KC mice." (PMID 40777309, 2025). "Based on these studies, we speculated that the HER2/AKT/NF-κB pathway could participate in the regulation of netrin-1 in pancreatic cancer." (PMID 26393880, 2015). "Similarly, in pancreatic cancer cell line MiaPacA, where 5FU and Doxorubicin have been shown to upregulate netrin-1 and its receptors, co-treatment of 5FU or Doxorubicin and TRAP-netrinUNC5A potentiated cell death." (PMID 24293316, 2013). "Given our previous report that NGF expression in pancreatic tumor cells is induced by β-adrenergic stimulation through the MAPK pathway, we examined this possibility for NTN1 expression." (PMID 40777309, 2025). "Specific membrane proteins such as CD151 and Netrin-1, along with the ANXA6/LRP1/TSP1 complex, further enhance the invasiveness and migration capabilities of pancreatic cancer cells by participating in cell–cell interactions and signaling transduction." (PMID 38954230, 2024). "KC tumors from Ntn1-KO mice exhibited decreased phosphorylation of ERK, consistent with our previous report that decreased adrenergic innervation reduces ERK activation in pancreatic tumor cells." (PMID 40777309, 2025). "There are several specific exosomes that can contribute to liver metastasis in pancreatic cancer via forming an inflammatory and immunosuppressive microenvironment in the liver, e.g., macrophage migration inhibitory factor (MIF), Integrin ITG αvβ5, Netrin-1, Lin28B and CD44." (PMID 38954230, 2024).
non-small cell lung carcinoma (8 papers, 2013 to 2025). A group of at least three distinct histological types of lung cancer, including non-small cell squamous cell carcinoma, adenocarcinoma, and large cell carcinoma. "Overexpression of netrin-1 has been associated with tumor progression in metastatic breast cancer, non-Hodgkin lymphoma non-small cell lung cancer and poorly differentiated pancreatic adenocarcinoma." (PMID 29854303, 2018). "Moreover, NTN1 has also been associated with the occurrence, development, survival, and clinical parameters of kidney cancer and non-small cell lung cancer." (PMID 40051609, 2025). "Univariate analyses revealed netrin-1 expression as a significant factor associated with poor patient survival in the total cohort of brain metastasis patients and in sub-entities such as non-small cell lung carcinomas." (PMID 24647424, 2014). "We and others have shown that netrin-1 expression is upregulated in samples from breast, ovarian, pancreatic and non-small cell lung cancer patients and that interfering with the netrin-1 autocrine/paracrine loop triggers apoptosis of cancer cells in several models." (PMID 24293316, 2013).
bladder cancer (7 papers, 2014 to 2025). "Furthermore, receiver operating characteristic curve (ROC) analysis supported the muscle‐invasion diagnostic significance of urine NTN1 in bladder cancer patients, with an area under the curve of 0.758, 96% sensitivity and 67% specificity." (PMID 38546656, 2024). "Furthermore, netrin-1/UNC5B was closely associated with bladder cancer malignant pathological biological behavior." (PMID 24528886, 2014). "In conclusion, the current work suggested that miR‐214 reduces chemoresistance by targeting NTN1 in bladder cancer cell lines." (PMID 38546656, 2024). "Conversely, low PKC activity, low NTN1 expression and high UNC5B expression can increase the susceptibility of bladder cancer cells to chemical therapeutics." (PMID 38546656, 2024). "In conclusion, the current work indicates that miR‐214 reduces chemoresistance by targeting NTN1 in bladder cancer cell lines." (PMID 38546656, 2024). "Our group has reported the novel function of PKCα in bladder cancer where it regulates cell survival through the netrin-1/UNC5B pathway, and by targeting DICER, PKCα can also modulate apoptosis of UCC cell lines." (PMID 28629334, 2017). "The present study aims to investigating the clinical significance of PKC α, netrin-1 and UNC5B in bladder cancer as well as their association with malignant biological behavior of cancer cells." (PMID 24528886, 2014). "In this study, we detect the expression of netrin-1/UNC5B in the bladder cancer tissues as well as in the bladder cancer cell line on both the RNA and protein levels, we found that netrin-1/UNC5B was closely related to the activation of PKC alpha state." (PMID 24528886, 2014). "Netrin-1 expression was positively correlated with histological grade, T stage, metastasis and poor prognosis in bladder cancer tissues." (PMID 24528886, 2014). "Consequently, PKCα and NTN1/UNC5B work together to regulate the effects of cisplatin on bladder cancer cells through a positive feedback regulatory loop." (PMID 38546656, 2024). "Therefore, we need to validate that PKC α inhibits bladder cancer cell apoptosis by regulating signaling pathway of netrin-1/UNC5B." (PMID 24528886, 2014). "In addition, cisplatin may increase NTN1 protein expression in bladder cancer cells, whereas miR214 mimics may partially prevent this effect." (PMID 38546656, 2024). "Furthermore, cell proliferation, migration and cell cycle progression were promoted with PMA treatment while inhibited by calphostin C. In addition, PMA treatment could induce while calphostin C reduce netrin-1 expression in bladder cancer cells." (PMID 24528886, 2014). "Unc5b is one of the common receptors of netrin-1 and netrin-1 -Unc5b pathway has been involved in PDAC tumors, bladder cancer and renal cell carcinoma." (PMID 35974411, 2022). "Netrin-1 and UNC5B expression was examined in 120 bladder cancer specimens using immunohistochemistry and in 40 fresh cancer tissues by western blot." (PMID 24528886, 2014). "Immunofluorescence showed elevated netrin-1 and decreased UNC5B expression in bladder cancer cells compared with normal bladder cell line." (PMID 24528886, 2014). "A negative connection was also detected between NTN1 and miR214 expression in bladder cancer tissues." (PMID 38546656, 2024). "Furthermore, strong PKC activity, high NTN1 expression and low UNC5B expression can improve bladder cancer cells cisplatin tolerance." (PMID 38546656, 2024). "The present study identified netrin-1/UNC5B, which could be regulated by PKC signaling, was important mediators of bladder cancer progression." (PMID 24528886, 2014).